FOLR3 (folate receptor gamma)
Description:
Binds to folate and reduced folic acid derivatives and mediates delivery of 5-methyltetrahydrofolate to the interior of cells. Isoform Short does not bind folate.
Synonyms: FR-gamma; FR-G; FRγ; FRgamma; gamma-hFR
Tractability: Antibody: its Gene Ontology location is reachable by antibodies, with high confidence; UniProt places it where antibodies can reach, with medium confidence; UniProt predicts a signal peptide or a membrane-spanning region.
Gene: Protein-coding gene on chromosome 11 (72,114,869 to 72,141,085, forward strand). Ensembl gene ENSG00000110203.
Subcellular location: Secreted
Pathways (Reactome):
Immune System: Neutrophil degranulation
Gene Ontology:
Molecular function: protein binding; folic acid binding; folic acid receptor activity; signaling receptor activity
Biological process: folic acid transport; cellular response to folic acid
Cellular component: extracellular region; extrinsic component of membrane; membrane; plasma membrane; specific granule lumen; tertiary granule lumen
Genetic constraint (gnomAD): Loss-of-function variants: 7 observed, 17.4 expected, observed/expected ratio (o/e) 0.4, 90% interval 0.23 to 0.76. The upper end of that interval is the gene's LOEUF score, 0.76, which puts it in group 3 of 6, group 1 being the genes least tolerant of losing a copy. Missense variants: 289 observed, 309.91 expected, observed/expected ratio (o/e) 0.93, 90% interval 0.85 to 1.03. Synonymous variants: 114 observed, 109.7 expected, observed/expected ratio (o/e) 1.04, 90% interval 0.89 to 1.21.
Homologues: Orthologues: chimpanzee FOLR3 (98% identical), tropical clawed frog folr1 (49% identical), zebrafish folr (49% identical). Paralogues in human: FOLR2 (81% identical), FOLR1 (72% identical), IZUMO1R (55% identical), RTBDN (17% identical).
Diseases named in the same sentence as FOLR3 in open-access papers:
FOLR3 is named in the same sentence as 17 diseases in open-access papers, as found by Europe PMC text mining. Sharing a sentence is not in itself a finding about the gene and the disease. The quoted sentences say what the papers report.
ovarian carcinoma (3 papers, 2012 to 2023). A malignant neoplasm originating from the surface ovarian epithelium. "We found folate receptor FOLR3 to be upregulated in metabolic subtype-2 samples, and its overexpression has been reported in ovarian cancer." (PMID 36984849, 2023). "The protein folate receptor-gamma (FR-gamma/FOLR3) was not included in these analyses because it was expressed at high levels in a subset of serum samples that did not correlate with ovarian cancer status." (PMID 35804849, 2022).
COVID-19 (1 paper, 2023). A disease caused by infection with severe acute respiratory syndrome coronavirus 2. "For instance, IL1B, NFKB1, NLRP3, PYCARD, and CASP1 are listed in the COVID-19 Disease Map, while there are molecules absent from it, including CCL3, 3L1, 4L2, CXCL1, 2, 3, 5, 16, TNFAIP6, C15orf48, TMEM176A/B, NFE2, PADI4, RAB20, ETS2, PHLDA2, FOLR3, and HP." (PMID 37719701, 2023).
hyperhomocysteinemia (1 paper, 2020). A serious metabolic condition caused by mutations in the MTHFR gene, medications, or nutritional deficiency. "The upregulation of FOLR3 and supplementation of folic acid can be advantageous treatment strategies for hyperhomocysteinemia patients and for the prevention of Hcy-related diseases." (PMID 32581311, 2020).
schistosomiasis (1 paper, 2023). An infectious disease caused by parasitic trematodes of the genus Schistosoma that colonize human blood vessels and release eggs that can cause granulomatous reactions leading to acute (swimmer's itch or acute schistosomiasis syndrome) or chronic disease. "This preliminary result offers evidence that FOLR3 might play a potential role in the development of advanced schistosomiasis, though more studies are needed to investigate this relationship." (PMID 37817226, 2023).
tumor (3 papers, 2018 to 2024). "Considering the associations of FOLR3 methylations with tumor stage and their differences between LUSC and LUAD, the FOLR3 methylation profiles in LUSC and LUAD were further investigated individually." (PMID 38273401, 2024). "For the LUSC patients of different races, African-American were shown to have significant lower FOLR3 promoter methylation than Caucasian patients in their tumor tissues." (PMID 38273401, 2024). "As FOLR3 hypomethylation was presented to be more significant in larger LUAD/LUSC tumors (> 3 cm) than the smaller ones, a significant association of FOLR3 hypomethylation with tumor proliferation and progression could be deduced." (PMID 38273401, 2024). "After removing the individual samples from the database, we obtained 20 pairs of paired samples and then compared the expression levels of CCL20, SCG5, SPP1, FOLR3, and KRT75 genes in tumor tissues vs. normal tissues." (PMID 36684241, 2022).
FOLR3 also shares sentences with these, for which no sentence is quoted: cancer (4 papers); bladder cancer (1); breast carcinoma (1); cardiovascular diseases (1); coronary artery disease (1); infection (1); Insulin resistance (1); malignant mesothelioma (1); mesothelioma (1); Obesity (1); osteoporosis (1); viral infection (1).